INS (insulin)
Diseases named in the same sentence as INS in open-access papers (continued):
Sharing a sentence is not in itself a finding about the gene and the disease.
Hepatic steatosis (continued). "Dietary zinc intake did not alter hepatic steatosis, creatinine clearance, or levels of proteins that contribute to insulin signaling, inflammation or zinc transport in epididymal fat." (PMID 38931174, 2024). "In hepatic steatosis mice, CD36 deletion reduced liver lipid content and could also contribute to improved insulin sensitivity." (PMID 39524404, 2024). "It seems likely that when MAFLD and T2D co-exist, the role of hyperinsulinaemia in the pathogenesis of hepatic steatosis and MAFLD development would have a greater impact in the early stages of T2D development when β-cell insulin release is still relatively preserved." (PMID 37367914, 2023). "Because insulin signaling is required for lipogenic activity of the glucocorticoid in the liver, activation of AMPK and insulin resistance pathways prevented lipogenesis and hepatic steatosis in laying hens under stress." (PMID 37560158, 2023). "This suggests that the improvement in liver steatosis and insulin sensitivity seen in FGFR4 KD mice are not dependent on hepatic FXR activation." (PMID 36586437, 2023). "We found that the mean AIP, BMI, HOMA-IR, and insulin levels of obese adolescents with fatty liver were higher than those of obese adolescents without fatty liver and the healthy control group." (PMID 37189890, 2023). "Hepatic steatosis or fatty liver is the first hit in NAFLD pathogenesis, wherein lipotoxicity from the accumulated lipids induces oxidative stress, insulin resistance, inflammation, and fibrosis, leading to the development of non-alcoholic steatohepatitis (NASH)." (PMID 37503004, 2023). "In this study, we found that the traditional Chinese medicine PPL significantly ameliorated overweight, fasting insulin, hyperlipemia and improved hepatic steatosis in mice, without significant effect on their food intake." (PMID 37033635, 2023). "Conversely, others demonstrate that MGAT1 knockout in liver does not improve hepatic steatosis, liver TG content, insulin sensitivity or glucose tolerance in HFD-fed mice." (PMID 36837793, 2023). "In contrast, when expressed exclusively in liver, ACOTT11 leads to hepatic steatosis and diminished rates of fatty acid oxidation without affecting glucose tolerance or insulin sensitivity." (PMID 36755289, 2023). "The mean BMI, HbA1c, HOMA-IR, and insulin levels of those with fatty liver were considerably higher than those without fatty liver and the healthy control group (p < 0.05)." (PMID 37189890, 2023). "A-KO mice showed no obvious differences in blood glucose/insulin levels, hepatic triglyceride levels or hepatic steatosis severity versus control mice, under the pre-hepatectomy condition of 16-week HFD feeding." (PMID 36690638, 2023). "In an animal study on insulin resistant rats, it has been shown that activation of ATR1 contributed to protein oxidation, impaired hepatic lipid and antioxidant metabolism and promotion of hepatic steatosis." (PMID 37189076, 2023). "• Hepatic steatosis and triglyceride were more obvious in O-GDM or O-PGDM. • Maternal diabetic offspring hepatocytes secreted more pro-inflammatory factors. • Liver insulin sensitivity and glucose infusion were impaired in diabetic offspring." (PMID 37255932, 2023). "In conclusion, Peptide 2 supplementation improved insulin sensitivity and decreased hepatic steatosis, unlike the insulin-sensitizing drug rosiglitazone." (PMID 36837793, 2023). "IH exposure decreased body weight gain, attenuated liver steatosis and decreased hepatic lipid content but did no change in either glucose tolerance or insulin sensitivity." (PMID 36873991, 2023). "In mice, HFD reduces Enho mRNA levels concomitantly with the development of hepatic steatosis, while adropin overexpression attenuates HFD-derived hepatic steatosis, reduces weight gain, increases whole-body fatty acid oxidation, and improves insulin sensitivity." (PMID 36014766, 2022).
Hepatic steatosis (continued). "Indeed, GLP-1 is closely related to hepatocyte fatty acid β-oxidation and insulin sensitivity, and GLP-1R in hepatocytes modulated insulin signaling, thereby ameliorating hepatic steatosis." (PMID 35655996, 2022). "Here we show that ovariectomized female mice on a high-fat diet (HFD) present a similar degree of visceral adiposity, a greater body fat percentage, and an analogous degree of hepatic steatosis as HFD-fed male mice, yet present a significantly superior insulin sensitive phenotype." (PMID 36198723, 2022). "Administration of this HCD leads to the development of simple hepatic steatosis with little inflammation and no fibrosis, as well as a marked increase in serum insulin levels." (PMID 36555433, 2022). "The Fatty Liver Improvement with Rosiglitazone Therapy (FLIRT) (ClinicalTrials.gov Identifier: NCT00492700) study showed favorable effects of this agent on insulin sensitivity and ALT normalization and a significant 30% reduction in hepatic steatosis vs. placebo." (PMID 36295635, 2022). "In addition, the following were higher in women with hepatic steatosis: BMI, WC, WHR, total cholesterol, triglycerides, LDL, insulin, fasting glucose, HOMA-IR, HbA1c, AST, ALT, gamma glutamyl transferase (GGT) and ferritin." (PMID 36359239, 2022). "Adipocyte-specific deletion of PPARγ under the AdipoQ gene promoter leads to a nearly complete lack of AT, insulin resistance and massive liver steatosis, i.e. generalized lipodystrophy." (PMID 35250856, 2022). "In contrast, hepatic steatosis, glucose tolerance and insulin resistance were not affected in our experimental setup." (PMID 36297003, 2022). "The aim of this cross-sectional study was to assess the prevalence of carotid atherosclerosis, arterial stiffness, and fatty liver disease in a cohort of insulin-sensitive, non-obese, untreated FCH patients." (PMID 35892670, 2022). "CGA could alleviate HFD-induced hepatic steatosis and inflammation, reduce serum transaminase, FBG and blood lipids, increase insulin sensitivity." (PMID 34276380, 2021). "We evaluated the metabolic phenotypes of LKO mice with global deficiency of GDF15 or FGF21 and show that GDF15 regulates body and fat mass and prevents diet-induced hepatic steatosis, whereas FGF21 upregulates insulin sensitivity, energy expenditure, and thermogenesis in white adipose tissue." (PMID 33718833, 2021). "Therefore, ATM-derived exosomal miRNA critically regulates liver insulin sensitivity, which is also expected to generate profound consequences on liver DNL, thereby hepatic steatosis." (PMID 34943809, 2021). "Together with the unchanged liver mass, this suggested, that continuous ingestion of the amine lowered blood glucose at the expense of enlarged subcutaneous fat mass but without worsening insulin responsiveness and without promoting hepatic steatosis." (PMID 34444782, 2021). "Monounsaturated fatty acids (MUFAs) were known to suppress hepatic inflammation and ROS production, increase insulin sensitivity, and provide protective effects against NAFLD, although MUFAs might increase hepatic steatosis." (PMID 36994336, 2021). "Aramchol (arachidyl-amido cholanoic) has some beneficial effects on liver steatosis in humans but does not improve liver enzymes, glucose metabolism, and insulin sensitivity." (PMID 34065331, 2021). "Intriguingly, although the male progenies of the third and fourth generations of WD5 males were overweight, they did not develop metabolic alterations, such as glucose/insulin sensitivity alterations and fatty liver diseases." (PMID 33783350, 2021). "In either case, this study demonstrates that impaired glucose homeostasis and insulin desensitation are not required for MBOAT7-induced fatty liver disease." (PMID 32859645, 2021).
Hepatic steatosis (continued). "A higher concentration of eHsp70 suggests the development of fatty liver (due to a higher NEFA to cholesterol ratio and lower LFI) and insulin resistance (due to a lower revised quantitative insulin sensitivity check index RQUICKI-BHB and higher NEFA to insulin ratio)." (PMID 35050141, 2021). "Hepatic steatosis has been evidenced in the present study with elevated sera liver function biomarkers, ALT and AST levels and increased hepatic TG and TC contents as well as distorted serum levels of insulin, adiponectin, and Apo B100." (PMID 32420546, 2020). "Elevated insulin and increased substrate delivery to the liver promotes hepatic steatosis by driving increased de novo lipogenesis without increasing glucose uptake." (PMID 33108366, 2020). "As a consequence, lipids can only be stored ectopically in non-adipocytes with the major health consequences as fatty liver and insulin resistance." (PMID 33233602, 2020). "AiPKO mice, where Pten was deleted in mature adipocytes, maintained insulin sensitivity despite putting on (mainly)SAT on high fat diet; knocking out Pten after HFD-induced weight gain restored insulin sensitivity and reduced hepatic steatosis." (PMID 32582754, 2020). "After 56-day treatment, the curcumin-treated group experienced a significant improvement in fasting plasma insulin (FPI), HOMA index, waist circumference, blood pressure, triglycerides (TG), HDL-C, liver transaminases, gamma-GT, index of liver steatosis and serum cortisol compared to the baseline." (PMID 30796508, 2020). "To conclude, even though VD supplementation did not improve body weight and insulin sensitivity, interesting data were generated in regard to the impact of VD supplementation on hepatic steatosis and adipose tissue inflammation." (PMID 32012987, 2020). "Furthermore, supplementation with CSP increased the levels of inflammation, serum TG, blood glucose, insulin, and ALT and the degree of liver fat accumulation, fibrosis, hepatic steatosis and steatohepatitis." (PMID 32512581, 2020). "Our findings also provide the first evidence of the inhibitory role of insulin on the basal expression of GLP-1R, which might explain why liraglutide could alleviate the insulin aggravated hepatic steatosis." (PMID 33746742, 2020). "Oral treatment of age-related hepatic steatosis either with BDS (450 mg/kg), PDS (30 mg/kg), CDS (30 mg/kg) or ZH (250 μg/kg) regulated the serum levels of adiponectin, Apo B100, and insulin, whereas adiponectin levels were elevated by about 2.6, 2.3, 2.4, and 3.1 folds, respectively." (PMID 32420546, 2020). "Furthermore, NSG mice have been demonstrated to be more insulin sensitive when fed with high fat diet than C57BL/6 mice, while still developing hepatic steatosis." (PMID 33013934, 2020). "Serum concentration of leptin (20.64 ± 22.02 ng/ml versus 9.97 ± 11.97 ng/ml) and insulin (15.81 ± 17.73 μU/ml versus 8.80 ± 7.07 μU/ml) were significantly higher in patients with hepatic steatosis compared to those without hepatic steatosis (P < 0.001)." (PMID 32728230, 2020). "Linagliptin improved OSI-906-induced hepatic steatosis via an insulin-signaling-independent pathway, without altering glucose levels, free fatty acid levels, gluconeogenic gene expressions in the liver, or visceral fat atrophy." (PMID 33105604, 2020). "We found that L-Mttp−/− mice develop hepatic steatosis at an early age but do not develop hepatic insulin resistance." (PMID 32907986, 2020). "More subjects with fatty liver used antihyperglycemic, insulin and antihypertensive therapy, than those without fatty liver." (PMID 33269025, 2020). "We demonstrate that RDX8940, a potent, selective, minimally systemic oral TGR5 agonist, improves liver steatosis and insulin sensitivity in a mouse model of NAFLD and does not inhibit gallbladder emptying in mice." (PMID 30605011, 2019).
Hepatic steatosis (continued). "It should be mentioned that not all antidiabetic drugs are efficacious against liver steatosis; for example, insulin and insulin secretagogues seem to exacerbate steatosis and increase the risk of HCC." (PMID 31010049, 2019). "Our study population was selected to have fatty liver disease by ultrasound and likely more insulin resistant than individuals without fatty liver disease." (PMID 31308382, 2019). "At the conclusion of therapy, 40 to 43% of patients no longer had a fatty liver, and in the exenatide group, 0 out of 6 patients (0%) still had severe disease compared with 3 out of 5 patients (60%) in the insulin group (P = 0.03, our analysis)." (PMID 31783920, 2019). "Our results indicate that the beneficial effects of the PPE on hepatic steatosis and insulin sensitivity were not secondary to the reduction in body mass and food intake." (PMID 29599925, 2018). "Further analysis demonstrated that reduced energy expenditure in brown adipose tissue and hepatic steatosis, but not white adipose tissue inflammation, was responsible for the insulin resistant phenotype." (PMID 30304866, 2018). "Despite eating, surgical re-routing of the gut may prevent weight accumulation, regulate glucose-lipid metabolism and insulin sensitivity, control a chronic inflammatory state, change the secretion pattern of FGF21 and alleviate the severity of fatty liver." (PMID 30355361, 2018). "An increased HOMA-IR index, as can also be seen in the results of the present study, indicates altered insulin sensitivity, not only in overweight subjects who do not have fatty liver changes, but also in those of normal weight with fatty liver disease." (PMID 29409538, 2018). "For example, a number of mouse models that develop fatty liver disease are not insulin resistant, and some people with NAFLD develop fibrosis without preceding inflammatory conditions typical for non-alcoholic steatohepatitis (NASH)." (PMID 29558460, 2018). "Low levels of alcohol consumption improve insulin sensitivity, enhance hepatic blood flow, and increase the adiponectin levels; these effects might support our finding that cigarette smoking accompanied by low intakes of alcohol is not a risk factor for the onset of fatty liver disease." (PMID 29664906, 2018). "By multivariate analysis, body mass index (BMI), fasting insulin, homeostasis model assessment index (HOMA-IR), and fasting blood glucose (FBG) are positively associated with the hepatic steatosis in different ethnicities independent of HBV infection." (PMID 28695131, 2017). "In high-fat diet–fed mice, low temperature exposure improved browning of visceral fat, global metabolism via nonshivering thermogenesis, insulin sensitivity, and hepatic steatosis." (PMID 28239649, 2017). "Using multivariable linear regression analyses, estimated morning and evening GI, GL, low-GI-CHO (GI < 55) and higher-GI-CHO (GI ≥ 55) were related to insulin sensitivity (N = 252), hepatic steatosis index (HSI), fatty liver index (FLI) (both N = 253), and a pro-inflammatory-score (N = 249)." (PMID 28604592, 2017). "Overall, morning GI and GL as well as morning carbohydrate intake from low- or higher-GI sources were not related to insulin sensitivity, the primary hepatic steatosis outcomes HSI and FLI or the pro-inflammatory score (top) in young adulthood (all p > 0.1)." (PMID 28604592, 2017). "However, it is clear that APS markedly reduced HFSTZ-altered body weight, fasting serum insulin level, MOMA-IR, serum leptin level, hepatic TG and hepatic steatosis." (PMID 29258283, 2017). "PPARγ activation in liver contributes to hepatic steatosis and is not indispensable for insulin sensitization, depending on the diverse rodent backgrounds studied." (PMID 28611668, 2017). "And hepatic steatosis was attenuated in the absent of improved serum fasting glucose, insulin level or HOMA-IR." (PMID 28484247, 2017).
Hepatic steatosis (continued). "In previous unpublished experiments, we observed that mice with fatty liver induced by diet-induced obesity (DIO) and treated with niclosamide had lower liver triglycerides and improved insulin sensitivity compared to untreated mice, which has been independently confirmed." (PMID 28437447, 2017). "This study demonstrated a significant improvement in insulin sensitivity and hepatic steatosis with the MedDiet compared to no change in the low fat diet group." (PMID 26831892, 2016). "In contrast there was no significant improvement in insulin sensitivity and only a 7 % reduction of hepatic steatosis with the low fat, high carbohydrate diet." (PMID 26831892, 2016). "These mice were observed to develop marked hepatic steatosis in the absence of any abnormalities in plasma glucose and insulin levels, glucose and insulin tolerance, or infusion rates during hyperinsulinaemic euglycaemic clamp experiments." (PMID 26978356, 2016). "Oral administration of RR6 for 8 days completely inhibited plasma vanin activity, but did not affect hepatic glucose production, insulin sensitivity or hepatic steatosis in ZDF-diabetes rats." (PMID 26932716, 2016). "Taken together, our results demonstrate that hepatic steatosis in Pld1−/− mice is not coupled with insulin resistance." (PMID 27976696, 2016). "In summary, the results of this study demonstrate that a decrease in PA production by lysosomal PLD1 inhibits autolysosome formation in the Pld1−/− liver, leading to hepatic steatosis, without affecting insulin sensitivity." (PMID 27976696, 2016). "INS, PPARA, LEP, SREBF1, and ALB are the introduced biomarker panel for fatty liver disease." (PMID 28224024, 2016). "Overall, our data and recent publications indicate that a low-calorie diet and lifestyle changes rapidly reduce fatty liver disease in obese diabetics with and without insulin therapy." (PMID 27110719, 2016). "While some studies do suggest that T2 has clinical utility, our data demonstrate that T2 does not reduce hepatic steatosis or improve hepatic insulin sensitivity in in safflower-oil fed male SD rats." (PMID 26485433, 2015). "This study demonstrates clearly that the amelioration of hepatic steatosis by TR agonists is not sufficient to improve insulin sensitivity, at least in ob/ob mice." (PMID 25849936, 2015). "In that study, much like the current findings, it was shown that while both GC-1 and KB2115 reduced hepatic steatosis substantially, neither compound elicited improvements in insulin sensitivity." (PMID 25849936, 2015). "This study is the first to describe the mechanism of CCR2 inhibitor in hepatic steatosis, and supports the involvement cross talk between MCP-1 and CCR2, which could activate inflammatory responses and blunt insulin signaling in the fatty liver." (PMID 25816097, 2015). "Pharmacological activation of RXR with CNX-013-B2 can give strong glycemic and lipid control, improve insulin sensitivity without increasing body weight, enhance muscle oxidative capacity and function and has a potential to control hepatic steatosis." (PMID 25143786, 2014). "In insulin-resistant individuals with several metabolic disturbances, a high-MUFA diet was considered a good option for nutritional management of glucose and lipid metabolism, as well as hepatic steatosis." (PMID 25960776, 2014). "Possibility and severity of fatty liver in sonography was more in patients that had more waist circumference, more hip circumference, more serum TG, more serum FBS, more serum fasting insulin, more serum Alt, more systolic blood pressure, more HOMA index, and less serum alkaline phosphatase." (PMID 25031864, 2014). "Often, patients with NAFLD are obese or overweight and insulin resistant with higher energy intake with respect to individuals without hepatic steatosis." (PMID 25937854, 2014).